ENSG00000288681 (novel protein)
Gene: Protein-coding gene on chromosome 11 (308,408 to 315,272, forward strand). Ensembl gene ENSG00000288681.
Genetic constraint (gnomAD): Loss-of-function variants: 1 observed, 2.68 expected, observed/expected ratio (o/e) 0.37, 90% interval 0.13 to 1.57. That is too few expected variants to judge how well the gene tolerates losing a copy. Missense variants: 63 observed, 99.52 expected, observed/expected ratio (o/e) 0.63, 90% interval 0.52 to 0.78. Synonymous variants: 41 observed, 40.56 expected, observed/expected ratio (o/e) 1.01, 90% interval 0.79 to 1.31.